EPO (erythropoietin)
Diseases named in the same sentence as EPO in open-access papers (continued):
Sharing a sentence is not in itself a finding about the gene and the disease.
leiomyoma (3 papers, 2014 to 2025). A well-circumscribed benign smooth muscle neoplasm characterized by the presence of spindle cells with cigar-shaped nuclei, interlacing fascicles, and a whorled pattern. "We believe the principal mechanism underlying MES is the ectopic production of erythropoietin (EPO) by the leiomyoma tissue itself." (PMID 41487860, 2025). "As a result, it was found that the cytoplasm of the leiomyoma cells was strongly positive for erythropoietin." (PMID 24551466, 2014). "We experienced a case of myomatous erythrocytosis syndrome, which was diagnosed by detecting erythropoietin in a leiomyoma using an immunohistochemical method." (PMID 24551466, 2014). "We consider the ectopic production of EPO by the leiomyoma the leading hypothesis for the pathophysiology of MES." (PMID 41487860, 2025). "First, a local autocrine/paracrine effect may be at play, as leiomyomas also express EPO receptors; locally produced EPO could be utilized within the tumor for growth and angiogenesis without being released into systemic circulation." (PMID 41487860, 2025). "In addition, immunostaining demonstrated that the cytoplasm of the leiomyoma cells was strongly positive for erythropoietin." (PMID 24551466, 2014).
lupus nephritis (3 papers, 2013 to 2022). Glomerulonephritis in the context of systemic lupus erythematosus. "In pristane-induced lupus nephritis, EPO deficiency selectively on CD4+ T cell resulted in increased susceptibility to the disease (more proteinuria and severe renal involvement) and conferred resistance to the inhibitory effects of EPO on Th17 cell induction." (PMID 33796104, 2021). "In these models of lupus nephritis, in which Epo gene expression is reduced, EPO treatment prevents Th17 cell induction and increases the Treg/Th17 and Th2/Th1 cell ratio." (PMID 33796104, 2021). "Erythropoietin (EPO) also has its special challenge in lupus nephritis." (PMID 25340141, 2013).
macular edema (3 papers, 2018 to 2025). "This suggests that hypoxia stimulates the release of inflammatory mediators and vasoproliferative factors, including VEGF and erythropoietin (EPO), which are capable of increasing vascular permeability and contribute to the development of macular edema and more severe forms of DR." (PMID 29615813, 2018). "Additionally, we concentrated on several genes presumed to play a role in the pathophysiology of macular edema: VEGFA, VEGFC, EPO, NOS3 (eNOS), PLVAP, and APOE4." (PMID 40455044, 2025).
metastatic carcinoma (3 papers, 2013 to 2024). A carcinoma which has spread from the original site of growth to another anatomic site. "Hepatocellular carcinoma, hepatoblastoma and metastatic carcinoma all producing EPO were described in horses." (PMID 36495211, 2023). "EPO and EPOR levels were only slightly increased in metastatic cancers without reaching significance (data not shown)." (PMID 24165569, 2013).
neovascular glaucoma (3 papers, 2012 to 2021). "The improvement in ocular perfusion following coronary artery bypass graft surgery, coupled with the administration of erythropoietin-stimulating factor, could have contributed to the onset and rapid progression of neovascular glaucoma." (PMID 29429414, 2018). "Unlike our patient, he did not have any PRP laser treatment performed before the onset of neovascular glaucoma, and he did not receive exogenous erythropoietin." (PMID 29429414, 2018).
obstructive uropathy (3 papers, 2013 to 2026). "A previous adult study even demonstrated decreased EPO levels in the population with partial unilateral urinary obstruction." (PMID 39767963, 2024).
ocular hypertension (3 papers, 2016 to 2022). Abnormally high intraocular pressure. "Additionally, neutralization of endogenous EPO with sEPOR exacerbated ocular hypertension-related RGC loss." (PMID 36555679, 2022). "Two weeks after ocular hypertension, the levels of EPO protein and EPOR significantly increased by 1.5 and 3 times compared to normal retina, respectively." (PMID 36555679, 2022). "In a rat induced-model of ocular hypertension, erythropoietin, which may be protective against hypoxic injury, was shown to reduce HIF-1 expression and to prevent deficits in the ERG b-wave, consistent with our results with O2-treatment." (PMID 35333901, 2022).
osteosarcoma (3 papers, 2014 to 2025). A usually aggressive malignant bone-forming mesenchymal neoplasm, predominantly affecting adolescents and young adults. "The major aim of this study using SELDI-TOF-MS combined with EPO-KB is to identify serum markers from human osteosarcoma sera as potential OS-associated markers for early diagnosis of OS." (PMID 24872957, 2014). "In the present study, we showed that EPO enhances the expression of M2 cytokines by TAMs in osteosarcoma lung metastasis patients, which led to the progression of cancers by different mechanisms." (PMID 32908942, 2020). "Using SELDI-TOF-MS combined with EPO-KB makes it possible to directly separate and identify the proteins from human osteosarcoma sera." (PMID 24872957, 2014). "We hypothesized that TAMs express EPOR, which is a main component of TAMs, and EPO enhances the protumor functions of EPOR+ macrophages to promote the progression of osteosarcoma lung metastasis." (PMID 32908942, 2020). "In conclusion, our study suggests that TAMs in osteosarcoma lung metastasis samples express EPOR and CD163+EPOR+ macrophages are true TAMs that can promote the progression of osteosarcoma lung metastasis under EPO stimulation." (PMID 32908942, 2020). "Taken together, we demonstrated that TAMs in osteosarcoma lung metastasis specimens were characterized by the expression of EPOR, suggesting that EPO may play a pivotal role not previously illustrated." (PMID 32908942, 2020).
periodontal disease (3 papers, 2022 to 2024). "For example, a temperature-sensitive polymer scaffolding was used to distribute drugs like aspirin, erythropoietin, and ornidazole to treat periodontal disease." (PMID 39605747, 2024). "On the other hand, we found three articles that study periodontal disease (EPO)." (PMID 39598089, 2024). "CS/b-GP/G/EPO/RLX hydrogels are effective for treating periodontal disease." (PMID 39605747, 2024). "Aspirin and erythropoietin-filled locally used hydrogels were demonstrated for the treatment of periodontal disease, and another recent example studied the combined application of CHX and ibuprofen in intra-pockets administration and proved their clinical relevance." (PMID 35631542, 2022).
peripheral arterial disease (3 papers, 2021 to 2024). A disorder of the arteries supplying the upper and lower extremity and the visceral organs. "Demographic and EPO rs1617640 genotype data ofperipheral arterial disease (PAD) patients." (PMID 39077006, 2023).
pituitary adenoma (3 papers, 2012 to 2017). "The authors suggest that EPO administration may promote the growth of pituitary adenomas by enhancing angiogenesis through EPO-JAK2-STAT3-VEGF signaling pathway and should be used with caution in anemia patients bearing pituitary adenoma due to its potential deleterious effects." (PMID 25426117, 2014). "Even more interestingly, EPO accelerated the tumor growth of rat prolactinoma MMQ pituitary adenoma xenografts lacking EPOR via the enhancement of angiogenesis in vivo, without a direct effect of EPO on MMQ cells in vitro." (PMID 28703764, 2017). "Even more interestingly, EPO accelerated the tumor growth of MMQ pituitary adenoma xenografts lacking EPOR via enhancement of angiogenesis in vivo, without a direct EPO effect on MMQ cells in vitro." (PMID 25426117, 2014). "Since the EPO-EPOR signaling has never been investigated in human pituitary adenomas, we first assessed the EPOR expression in 31 human pituitary adenoma samples using immunohistochemistry and Western blotting." (PMID 22086127, 2012).
primary myelofibrosis (3 papers, 2020 to 2022). Myelofibrosis with myeloid metaplasia is a myeloproliferative disease with annual incidence of approximately 1 case per 100,000 individuals and age at diagnosis around 60 (an increased prevalence is noted in Ashkenazi Jews). "Excessive secretion of PTH can cause bone marrow fibrosis, inhibit endogenous erythropoietin (EPO), suppress erythroid progenitors, and reduce red blood cell survival." (PMID 36142295, 2022). "Apart from the reversal of bone marrow fibrosis and enhanced erythropoietin production, we propose that the removal of excess PTH also contributed to improvement in iron-restricted erythropoiesis." (PMID 36142295, 2022).
rhabdomyolysis (3 papers, 2017 to 2021). Necrosis or disintegration of skeletal muscle often followed by myoglobinuria. "Moreover, EPO reduced macrophage infiltration and enhanced the phenotypic switch toward M2 macrophages in an experimental model of rhabdomyolysis-induced AKI." (PMID 33928100, 2021).
Salmonella Infections (3 papers, 2012 to 2024). Infections with bacteria of the genus SALMONELLA. "Specifically, EPO down-regulates pro-inflammatory immune effector pathways in response to chemical tissue damage, LPS stimulation and Salmonella infection." (PMID 22094132, 2012). "During Salmonella infection, accumulation of CECs in the spleen and increased EPO production are dependent on Myd88/TRIF signaling; EPO neutralization reduces the population of CECs in the spleen and slightly improves the host immune response." (PMID 39474425, 2024).
tauopathy (3 papers, 2019 to 2023). Neurodegenerative disorders involving deposition of abnormal tau protein isoforms (tau proteins) in neurons and glial cells in the brain. "The results presented in this proof-of-concept study thereby offer promise for the use of this BBB-penetrating EPO molecule for tauopathies, including AD." (PMID 37111315, 2023). "This is one of the first studies showing beneficial effects of EPO or its derivatives in a mouse model of tauopathy." (PMID 33504364, 2021). "In our laboratory's search for a potential anti-inflammatory/immunomodulatory agent for tauopathy therapeutics, we turned our focus to a peptide derivative of erythropoietin (EPO)." (PMID 33504364, 2021). "Our secondary objective was to use the GFAP-luc BLI model to investigate the effectiveness of a new erythropoietin (EPO) based therapeutic agent in the treatment of tauopathies." (PMID 31572168, 2019). "Along with our recently published brief supplementary study of assessing the effect of JM4 treatment on PS19 mice noninvasively using bioluminescence imaging of glia fibrillary acid protein, this is the first study showing beneficial effects of EPO or its derivatives in a mouse model of tauopathy." (PMID 33504364, 2021). "Given the potential protective effects of EPO on tauopathy, the current study aimed to investigate the effect of the BBB-penetrating EPO (cTfRMAb-EPO) on tau pathology." (PMID 37111315, 2023). "In our study, we found that chronic treatment with JM4, a small peptide derived from the first loop of human EPO, delayed the onset of neurological deficit and prolonged lifespan in the PS19 mouse, an animal model of tauopathy." (PMID 33504364, 2021). "In this preclinical in vivo study, we assess the effects of JM4, a 19’mer peptide derived from the first loop of human EPO, on the PS19 mouse, an animal model of tauopathy." (PMID 33504364, 2021). "However, the effect of cTfRMAb-EPO on hyperphosphorylated tau, the primary constituent of NFTs, which are a characteristic neuropathologic marker of tauopathies including AD, has not been studied." (PMID 37111315, 2023). "Yet, the effects of EPO or its derivative in animal models of tauopathy have not been investigated." (PMID 33504364, 2021).
ulcer (3 papers, 2010 to 2026). "When compared to a placebo, both EPO formulations significantly decreased pain, ulcer size, and salivary IL-2 levels (p < 0.001)." (PMID 41851196, 2026).
ulcerative colitis (3 papers, 2013 to 2023). An inflammatory bowel disease involving the mucosal surface of the large intestine and rectum. "In general, EPO signaling pathway appeared to be considerably altered in the malignant transition from ulcerative colitis to colorectal carcinogenesis." (PMID 23825635, 2013). "The elevated hypoxia-inducible factors (HIFs) level induced by hypoxic conditions in ulcerative colitis was a direct catalyst which accelerated the synthesis and release of EPO." (PMID 23825635, 2013). "Thus, high levels of EPO in ulcerative colitis led to the activation of EPO signaling pathway and therefore served as an anti-inflammatory factor against inflammation progression." (PMID 23825635, 2013). "The role of mitochondrial autophagy in ulcerative colitis nuclear factor called erythropoietin promotes mitochondrial autophagy Chinese medicine for ulcerative colitis Look for drugs with fewer side effects for ulcerative colitis To explore new ways to treat ulcerative colitis." (PMID 36705402, 2023).
Ventricular arrhythmia (3 papers, 2012 to 2024). "EPO treatment was observed to increase nNOS expression in ventricular myocytes, and EPO was protective in a mouse model of myocardial ischemia-reperfusion injury from CsCl-induced ventricular arrhythmia via nNOS activity." (PMID 38628440, 2024). "Furthermore, it would be valuable to study the EPO effect on ventricular arrhythmia and fibrillations following more severe CO poisoning." (PMID 24250553, 2012).
Abdominal obesity (2 papers, 2012 to 2024). Excessive fat around the stomach and abdomen. "However, erythropoietin levels are related only with abdominal obesity." (PMID 23016887, 2012).
acute erythroid leukemia (2 papers, 2012 to 2025). An acute myeloid leukemia characterized by a predominant immature erythroid population. "To elucidate the mechanism underlying its efficacy, we performed RNA-seq analysis in the EPO-dependent human acute erythroid leukemia cell line F36E cells." (PMID 40076818, 2025). "MTT bioassays (human erythroblastic leukemia cell proliferation) were performed to evaluate the activity of the recombinant rfEPO produced in lentiviral EPO vector-infected cells." (PMID 23028782, 2012).
acute pancreatitis (2 papers, 2014 to 2021). An acute inflammatory process that leads to necrosis of the pancreatic parenchyma. "In this study, the effects of EPO on pulmonary mast cells and on secondary injury caused by acute pancreatitis are investigated." (PMID 24761770, 2014). "Administration of EPO reduces the mast cell count and lung wall thickness, and it reduces the alveolar hemorrhage and septal infiltration induced by acute pancreatitis." (PMID 24761770, 2014).
allergic asthma (2 papers, 2022 to 2023). A asthma with a basis in a pathological type I hypersensitivity reaction. "Therefore, prebiotics may show lower effect than probiotics on control of eosinophilic airway inflammation, EPO activity, immune-allergic response, and allergic asthma." (PMID 35296330, 2022). "Since eosinophils are the most important effector cells in our allergic asthma model, we measured EPX and EPO, the granular proteins secreted when eosinophils are activated in the lung tissue by western blot." (PMID 37315181, 2023).
anthrax (2 papers, 2013 to 2014). "For clinical view, combined administration of EPO and second-generation of thrombopoietic agents, such as romiplostim and eltrombopag, will be used as a potential approach to treat anthrax." (PMID 23977125, 2013). "Given that EPO treatments are beneficial for LT-challenged mice, we hypothesized that combining G-CSF and EPO may be useful in treating anthrax." (PMID 25384016, 2014). "One critical aspect of G-CSF is the rapid induction of peripheral RBCs, a property superior to EPO, which may be applied to anthrax or other diseases with urgent RBC and oxygen demands." (PMID 25384016, 2014).
asthenia (2 papers, 2008 to 2024). Clinical sign or symptom manifested as debility, or lack or loss of strength and energy. "Recombinant human erythropoietin (rHu-Epo) was administered to six patients (8.7%) As far as non-haematological toxicity is concerned, grade 3 asthenia was registered in only four patients (5.8%) and nausea/vomiting (grade 3) occurred in one patient." (PMID 18493232, 2008).
attention deficit-hyperactivity disorder (2 papers, 2022 to 2024). A disorder characterized by a marked pattern of inattention and/or hyperactivity-impulsivity that is inconsistent with developmental level and clearly interferes with functioning in at least two settings (e.g. at home and at school). "EPO levels have been investigated in generalized anxiety disorder in adults and attention deficit hyperactivity disorder in children." (PMID 38995319, 2024).
Bartter syndrome (2 papers, 2015 to 2018). "Elevated hematocrit levels in Bartter syndrome might be caused not only by hemoconcentration but by elevated EPO production." (PMID 29535446, 2018).
bladder cancer (2 papers, 2016 to 2019). "Similarly, the GSE13507 dataset also suggested levels of KIAA0101 and EPO expression were negatively associated with the overall survival rate in bladder carcinoma patients (p < 0.05)." (PMID 26575329, 2016). "EPO gene could induce ERK1/2 phosphorylation and increase MMP-9 expression in both bladder cancer cells and vascular smooth muscle cells." (PMID 30915348, 2019).
Blindness (2 papers, 2021 to 2023). Blindness is the condition of lacking visual perception defined as a profound reduction in visual perception. "Here we report a delayed reversal of methanol-induced blindness in an adult by a combination of erythropoietin and a high dose of methylprednisolone." (PMID 37076901, 2023).
bone fracture (2 papers, 2021 to 2024). "The potential for endogenous EPO to affect bone health in human was observed in a study of bone fracture in elderly Swedish men with normal renal function that revealed high endogenous levels of EPO correlated with increased fracture risk." (PMID 34603036, 2021). "However, the risk of osteoporotic wrist fractures was significantly different between EPO users and non-EPO users in women (aSHR = 2.99, 95% CI = 1.55–5.40), but not in men." (PMID 39835325, 2024).
Brain atrophy (2 papers, 2009 to 2020). Partial or complete wasting (loss) of brain tissue that was once present. "Functional recovery was faster and more efficient in the EPO-treated group and was associated with reduction in hemispheric brain atrophy 5 weeks after the induction of ICH." (PMID 20142991, 2009). "It is not clear to date which from the panoply of neurorestorative effects of EPO are responsible for the long-term prevention of trauma-induced brain atrophy, cognitive and neurobehavioral dysfunction." (PMID 20142991, 2009). "In our hands, EPO treatment significantly limited brain atrophy and ventricle enlargement." (PMID 33043002, 2020). "After EPO treatment, brain atrophy and ventricular dilatation were significantly reduced." (PMID 33043002, 2020).
brain hemorrhage (2 papers, 2014 to 2025). "However, the risks of brain hemorrhage and infarction in patients on hemodialysis with erythropoietin therapy remain unclear." (PMID 41244199, 2025).